APOB (apolipoprotein B)
Diseases named in the same sentence as APOB in open-access papers (continued):
Sharing a sentence is not in itself a finding about the gene and the disease.
hypobetalipoproteinemia (79 papers, 2007 to 2026). A group of lipoprotein metabolism disorders that are characterized by permanently low levels (below the 5th percentile) of apolipoprotein B and LDL cholesterol. "Hypobetalipoproteinemia caused by pathogenic variants of APOB should be considered in patients with low serum total and LDL cholesterol." (PMID 41514510, 2026). "The principal finding of this study in the NASH‐CRN cohort is a significant association between heterozygosity for a P/LP variant in APOB causing hypobetalipoproteinemia and increased steatosis grade: 2.4 versus 1.6 (p‐value 0.0028)." (PMID 41514510, 2026). "We found clinically relevant P/LP APOB variants that cause hypobetalipoproteinemia and have been associated in other studies with histological progression of liver disease in our cohort of patients with well‐characterised MASLD." (PMID 41514510, 2026). "Fourteen of these participants had the APOB c.10238del (NM_000384.2) or APOB c.7537C>T (NM_000384.2) variant, which are associated with familial hypobetalipoproteinemia, a rare monogenic condition characterized by low LDL-C levels, distinct from FH." (PMID 41511773, 2026). "Familial hypobetalipoproteinemia (FHBL) is a codominant disorder of lipoprotein metabolism derived from mutations in the APOB gene encoding for ApoB and characterized by low levels of LDL-cholesterol." (PMID 38662298, 2024). "Regarding patients with hypobetalipoproteinemia caused by mutations in the APOB gene, the two cases showed low CoQ values, while only one showed a low CoQ/Chol ratio, and the other showed low-normal values." (PMID 39199213, 2024). "This variant was mistakenly classified as a likely pathogenic variant associated with familial hypercholesterolemia type 2 (OMIM# 144010) at the time of reporting, while truncating APOB variants are associated with hypobetalipoproteinemia (OMIM # 615558)." (PMID 38740897, 2024). "Familial hypobetalipoproteinemia (FHBL) is an autosomal semi-dominant disorder usually caused by variants in the APOB gene that frequently interferes with protein length." (PMID 37384046, 2023). "Given that ApoB exists as ApoB-100 in the liver, defective translation of full-length ApoB leads to defective assembly of ApoB-containing lipoproteins from both enterocytes and hepatocytes, which is associated with familial hypobetalipoproteinemia." (PMID 36817150, 2023). "We found two APOB missense variants associated with hypobetalipoproteinemia and each variant was identified in two heterozygous individuals." (PMID 36329474, 2022). "Familial hypobetalipoproteinemia (FHBL) is mostly caused by premature termination codons in the APOB gene, a condition associated with fatty liver and steatohepatitis." (PMID 35457099, 2022). "Pelusi and others observed that individuals with NAFLD-HCC and APOB variants had a circulating lipid profile consistent with hypobetalipoproteinemia." (PMID 37138899, 2022). "Familial hypobetalipoproteinemia is a metabolic disorder mainly caused by mutations in the apolipoprotein B gene." (PMID 33708142, 2021). "We here describe a case of familial hypobetalipoproteinemia, resulting from a heterozygosity for the pathogenic Gln845Argfs∗18 mutation in the ApoB gene." (PMID 33708142, 2021). "Type VI patients can include Abetalipoproteinemia (ABL) due to mutations in the microsomal transfer protein, and Homozygous hypobetalipoproteinemia (HHBL) due to structural mutations in apoB." (PMID 34838008, 2021). "For example, a single nucleotide deletion in the human apolipoprotein B (apoB) gene causes hypobetalipoproteinemia." (PMID 33561268, 2021). "The others were not confirmed by Sanger sequencing (N = 3) or were downgraded (N = 11 classified as variants of uncertain significance and N = 1 APOB variant associated with hypobetalipoproteinemia)." (PMID 33546753, 2021).
hypobetalipoproteinemia (continued). "Familial hypobetalipoproteinemia is considered as autosomal codominant and most frequently caused by mutations affecting directly the ApoB gene leading to truncated forms of the protein." (PMID 33708142, 2021). "APOB mutations cause familial hypobetalipoproteinemia, while TM6SF2 mutations are associated with NAFLD and progression to NASH." (PMID 32907986, 2020). "Clinical phenotypes of familial hypobetalipoproteinemia (FHBL) are related to a number of defective apolipoprotein B (APOB) alleles." (PMID 32093271, 2020). "Most importantly, individuals carrying APOB mutations had a circulating lipid profile consistent with hypobetalipoproteinemia, providing functional validation of the pathogenicity of the genetic mutations identified." (PMID 30842500, 2019). "Familial hypobetalipoproteinemia is a genetic disorder caused by rare protein-truncating variants (PTV) in the gene encoding APOB (apolipoprotein B), the major protein component of LDL (low-density lipoprotein) and triglyceride-rich lipoprotein particles." (PMID 30939045, 2019). "Cases of ApoB deficiency in hypobetalipoproteinemia and abetalipoproteinemia result in retinitis pigmentosa." (PMID 28442497, 2017). "Mutations in several different genes can cause hypobetalipoproteinemia, the most common of which are a result of truncating mutations in the APOB gene." (PMID 26064709, 2015). "The raw variant list was analyzed for variants in the known SPG genes and since the patient's lipid profile was consistent with hypobetalipoproteinemia, the variants in APOB gene were also analyzed." (PMID 26064709, 2015). "The proband’s wife and children presented with familial hypobetalipoproteinemia and were heterozygotes for the novel apoB H1401R variant." (PMID 22658148, 2012). "ApoB H1401R variant was identified as possible cause of familial hypobetalipoproteinemia and resulted in a reduction of cholesterol esterification rate." (PMID 22658148, 2012). "The in silico classification of the apoB H1401R variant as probably damaging associated with the vertical transmission of moderate hypobetalipoproteinemia in the kindred support apoB H1401R as possible causative of FHBL." (PMID 22658148, 2012). "Mutations of APOB gene cause familial hypobetalipoproteinemia, a codominant disorder characterized by low plasma levels of LDL cholesterol and apoB." (PMID 22658148, 2012). "The most characterized APOB mutations are the ones found in familial hypobetalipoproteinemia (FHBL)." (PMID 20423497, 2010). "We postulate that this isoform, if assembled into VLDL and LDL, will have similar properties to the C-terminally truncated isoforms that have been described and characterized in kindreds with natural mutations in APOB causing hypobetalipoproteinemia." (PMID 17233885, 2007). "Furthermore, some missense APOB variants are associated with conditions such as hypocholesterolemia or hypobetalipoproteinemia, while others display incomplete penetrance." (PMID 40422968, 2025). "In humans, mutations present in APOB lead to familial hypobetalipoproteinemia." (PMID 38730451, 2024). "However, mutations in the apoB gene can cause familial hypobetalipoproteinemia and mutations in MTTP, which encodes MTP, cause abetalipoproteinemia." (PMID 37095219, 2023). "These mutations differ from truncation mutations in APOB associated with hypobetalipoproteinemia." (PMID 35910211, 2022). "The second group, novel PTVs, comprised 27 variants in 27 carriers and yielded four individuals: three with hypobetalipoproteinemia, all with various novel truncating mutations in APOB, and one individual with hypertrophic cardiomyopathy and frameshift deletion in MYH7." (PMID 34691145, 2021). "Thirdly, variants in APOB, responsible for hypobetalipoproteinemia, were collectively observed in a high proportion of Italian patients (15%), and there was a significant enrichment in pathogenic and truncating mutations in this gene in the overall cohort of NAFLD-HCC patients." (PMID 30842500, 2019).
hypobetalipoproteinemia (continued). "Four family members presented with hypobetalipoproteinemia and were found to be carriers of a novel missense variant of apolipoprotein B. Mutations in the APOB gene causing FHBL are mainly frameshift or nonsense mutations leading to truncated apoB forms, whereas missense mutations are very rare." (PMID 22658148, 2012). "Finally, in two patients (#10 and #11), we defined a genetic diagnosis of heterozygous APOB‐related Familial Hypobetalipoproteinemia (FHBL) due to the presence of heterozygous pathogenic/likely pathogenic variants in APOB gene (NM_000384.3: p.S2429X and c.3696 + 2 T>G, respectively)." (PMID 39945383, 2025). "Another mutant isoform seen in patients with familial hypobetalipoproteinemia, APOB87Padova, is caused by a single nucleotide deletion at the 5' end of exon 28, leading to a shortened isoform comprising the N-terminal 3968 residues of APOB plus a divergent C-terminal 37 amino acid sequence." (PMID 17233885, 2007). "The genetic abnormalities in APOB and MTP are well-established to be associated with the development of familial hypobetalipoproteinemia (FHBL) and abetalipoproteinemia (ABL), respectively, both of which are characterized by impaired ApoB secretion." (PMID 40180213, 2025). "Familial hypobetalipoproteinemia (FHBL) is an autosomal codominant genetic disorder characterized by the diminished secretion of ApoB48 and ApoB100 lipoproteins due to defects in the ApoB gene." (PMID 38393015, 2024). "Rare variants in Apolipoprotein B (APOB) predispose to MAFLD and they are responsible for the development of severe MAFLD and hypobetalipoproteinemia." (PMID 38662298, 2024). "Mutations in the APOB gene result in disorders of lipid metabolism, such as familial hypobetalipoproteinemia and familial ligand-defective ApoB100." (PMID 36050800, 2022). "Hypobetalipoproteinemia (HBL) is characterized by low plasma levels of apolipoprotein B (apoB) and low-density lipoprotein cholesterol (LDL-C), less than the fifth percentile for age and sex." (PMID 35457099, 2022). "The elevated serum ApoB levels, even with a normal level of LDL, often cause hypobetalipoproteinemia, normotriglyceridemic hypobetalipoproteinemia, and hypercholesterolemia." (PMID 34156559, 2021). "Defects in ApoB synthesis and secretion result in several human diseases, including abetalipoproteinemia and familial hypobetalipoproteinemia (FHBL1)." (PMID 34236046, 2021). "Various truncated forms of APOB have been found earlier to segregate with the familial hypobetalipoproteinemia phenotype (OMIM:615558)." (PMID 34691145, 2021). "We report three novel protein truncating variants in APOB and one in MYH7 observed in individuals with hypobetalipoproteinemia and hypertrophic cardiomyopathy, respectively." (PMID 34691145, 2021). "Similar to most patients with familial hypobetalipoproteinemia, pHypoβ presented reduced plasma cholesterol and ApoB levels, heightened plasmatic liver enzymes as well as a vitamin E level close to the lower reference limit." (PMID 33708142, 2021). "We sequenced the APOB gene in 29 Japanese hypobetalipoproteinemia families, as well as 57 973 individuals derived from 12 CHD case-control studies—18 442 with early-onset CHD and 39 531 controls." (PMID 30939045, 2019). "Hypobetalipoproteinemia (HBL) is defined by plasma concentrations of LDL-cholesterol (LDL-C) or apolipoprotein B (APOB) that are lower than the fifth percentile for age and sex." (PMID 30400945, 2018). "Familial hypobetalipoproteinemia is defined as apoB and LDL levels below the 5th percentile and seems to be due to several defects, including loss-of-function mutations of PCSK9 and/or mutations leading to truncation of apoB." (PMID 30558209, 2018). "Here, the aim of our study was to examine the prevalence and characteristics of rare and common variants of APOB and PCSK9 underlying the phenotype of hypobetalipoproteinemia in Korean subjects." (PMID 29036232, 2017).
hypobetalipoproteinemia (continued). "Familial hypobetalipoproteinemia (FHBL), the only CDDENT that is dominantly inherited, is associated with mutations in the APOB gene, encoding apolipoprotein B, which, together with triglycerides and other lipids, makes up the nascent chylomicron." (PMID 26747865, 2016). "Several mutations in the APOB, PCSK9, and MTP genes result in familial hypobetalipoproteinemia (FHBL) and abetalipoproteinemia (ABL) defined as low, or absent levels of apoB-100, and LDL-C in plasma." (PMID 26754661, 2016). "For example, ‘Hypobetalipoproteinemia, Familial, Apolipoprotein B (D052476)’ in MeSH is mapped to ‘hypobetalipoproteinemia (DOID:1390)’ in DO by MFI." (PMID 24146757, 2013). "Using ASO-induced alternative splicing of APOB mRNA, we have demonstrated that it is possible to induce the expression of a novel isoform of APOB that simulates hypobetalipoproteinemia, and which should reduce circulating LDL and cholesterol levels." (PMID 17233885, 2007). "However, we detected only a trend toward significance with ApoB and BMI, which is consistent with familial hypobetalipoproteinemia presenting with low BMI." (PMID 34504056, 2021). "Despite the frequently asymptomatic appearance of the heterozygous form of familial hypobetalipoproteinemia, strongly reduced plasma ApoB and LDL-cholesterol levels combined eventually with vitamin E levels below or at the limit of reference values are typical clinical features." (PMID 33708142, 2021). "Examples are hypobetalipoproteinemia caused by mutations in the gene encoding ApoB and in abetalipoproteinemia due to mutations in the gene encoding microsomal TG transport protein (MTP) that is responsible for the lipidation of ApoB." (PMID 33597924, 2020). "Among the single genes, we found a significant enrichment of variants in the APOB gene predisposing to familial hypobetalipoproteinemia (two variants in cases and none in controls, p = 0.047)." (PMID 30842500, 2019). "Therefore, the identification of APOB mutations in subjects with NAFLD-HCC would be to allow the diagnosis, in these cases mostly unrecognized, of familial hypobetalipoproteinemia in the first-degree relatives, allowing to establish adequate HCC surveillance." (PMID 30842500, 2019). "Supporting the validity of our selection algorithm, in patients for whom data were available carriage of APOB variants was associated with 46% higher HDL cholesterol and 44% lower triglycerides (p = 0.008 and p = 0.001, respectively), consistent with a hypobetalipoproteinemia phenotype." (PMID 30842500, 2019). "For instance, mutations within the apolipoprotein B (APOB) or proprotein convertase subtilisin kexin 9 (PCSK9) gene result in familial hypobetalipoproteinemia, characterized by low or absent plasma levels of apoB and LDL-C." (PMID 30355853, 2018). "Mutations in APOB or its regulatory region cause hypobetalipoproteinemia, normotriglyceridemic hypobetalipoproteinemia and hypercholesterolemia." (PMID 28947988, 2017). "Homozygous hypobetalipoproteinemia (Ho-HBL; OMIM 107730) is another extremely rare inherited disorder characterized by improper packaging and secretion of apoB-containing lipoproteins due to mutations in both alleles of the APOB gene." (PMID 25852563, 2015). "Abetalipoproteinemia and homozygous hypobetalipoproteinemia are classical Mendelian autosomal recessive and co-dominant conditions, respectively, which are phenotypically similar and are usually caused by bi-allelic mutations in MTTP and APOB genes, respectively." (PMID 29540175, 2018). "Hypobetalipoproteinemia is characterized by LDL-cholesterol and apolipoprotein B (apoB) plasma levels below the fifth percentile for age and sex." (PMID 35457099, 2022). "The ApoB <5thCent findings in the typical subjects, and in at least some of the AGRE subjects, are most likely due to familial hypobetalipoproteinemia, with a prevalence of 1:1000–1:3000 in the general population." (PMID 34504056, 2021).
hypobetalipoproteinemia (continued). "Familial hypobetalipoproteinemia (FHBL) is an autosomal dominant condition characterized by low plasma concentrations of total cholesterol, low-density lipoprotein cholesterol, and apolipoprotein B (apoB)." (PMID 26064709, 2015). "Two classic examples are abetalipoproteinemia and familial hypobetalipoproteinemia (FHBL), genetic conditions characterized by inadequate assembly and secretion of apolipoprotein B (apoB)-containing lipoproteins from hepatocytes." (PMID 24454851, 2014). "Firstly, translation of the APOB mRNA lacking exon 27 (skip 27 mRNA) would generate a C-terminally truncated isoform of APOB, APOB87SKIP27, which is similar to the C-terminal truncations seen in some patients with hypobetalipoproteinemia." (PMID 17233885, 2007). "APOB is the main apolipoprotein of chylomicrons and low‐density lipoproteins (LDL) and is the ligand for the LDL receptor, and the low or absent levels of APOB in plasma usually lead to familial hypobetalipoproteinemia and abetalipoproteinemia." (PMID 34997982, 2022). "It is among the genetic syndromes associated with congenital lipid malabsorption such as abetalipoproteinemia (ABL) and familial hypobetalipoproteinemia, a heterogeneous group of disorders characterised by a decrease of LDL-cholesterol (LDLc) and apolipoprotein B (Apo B)." (PMID 27520363, 2016). "Several mutations in the ApoB, proprotein convertase subtilisin/kexin type 9 (PCSK9), and MTP genes result in low or absent levels of ApoB and LDL cholesterol in plasma, which cause familial hypobetalipoproteinemia and abetalipoproteinemia." (PMID 25949827, 2015). "The PCSK9 polymorphism found in patient AD3 was found to be present at a higher frequency in a low LDL-C population than in a normal population and to segregate with the "apoB- negative" Familial Hypobetalipoproteinemia phenotype in 3 families." (PMID 21235735, 2011). "Unlike homozygous embryos in abetalipoproteinemia and hypobetalipoproteinemia (with ApoB and MTTP deletions, respectively), which developed malformations leading to embryo resorption, homozygous Sar1bdel/del and Sar1bmut/mut embryos revealed no macroscopic abnormalities at E18.5." (PMID 37558128, 2023). "Hypobetalipoproteinemias (HBLs) encompass a diverse range of disorders that are characterized by reduced levels of total cholesterol (TC), low-density lipoprotein-cholesterol (LDL-C), and apolipoprotein B (apoB) in the blood, which fall below the 5th percentile of the population distribution." (PMID 37384046, 2023). "A genetic defect in APOB may lead to NFLD, as in familial hypobetalipoproteinemia." (PMID 35154608, 2021). "Familial hypobetalipoproteinemia (FHBL) is a codominant genetic disorder characterized by reduced plasma levels of low-density lipoprotein cholesterol and apolipoprotein B. To our knowledge, no study on FHBL in Lebanon and the Middle East region has been reported." (PMID 34564380, 2021).